PSME3 (proteasome activator subunit 3)
Diseases named in the same sentence as PSME3 in open-access papers (continued):
Sharing a sentence is not in itself a finding about the gene and the disease.
tumor (29 papers, 2003 to 2025). "Moreover, PSME3 showed associations with immune infiltration and immune cells in the tumor microenvironment, indicating its potential role in shaping the cancer immune landscape." (PMID 38312840, 2024). "Using transgenic Psme3-/- mice and subcutaneous tumor grafts, we confirmed that silencing of Pa28γ suppresses tumor growth, reduces C1qbp levels, and dampens mitochondrial metabolism—specifically in knockout hosts." (PMID 40736231, 2025). "In summary, the correlation between PSME3 and immune checkpoint expression offers crucial insights into the intricate dynamics within the tumor microenvironment." (PMID 38312840, 2024). "We also focused on the role of PSME3 in the tumor immune microenvironment, which was further validated through flow cytometry analysis to gain a deeper understanding of its involvement in immune processes." (PMID 38312840, 2024). "The data indicates a correlation between the expression of PSME3 and the pathological staging as well as tumor metastasis in cases of LUAD, LIHC, and KIRC." (PMID 38312840, 2024). "Previous studies have reported that PSME3 expression is increased in tumor tissues compared to normal tissues and that it acts as an oncogenic driver in many types of cancers." (PMID 34650966, 2021). "The expression level of all PSME genes was significantly correlated with tumor stage for patients with GC, an effect that was especially pronounced for PSME3 and PSME4." (PMID 34650966, 2021). "In this report, we demonstrated that PSME3 is up-regulated in GC tumor tissues compared to normal tissues and that the upregulation of PSME3 is strongly related to unfavorable OS, FPS, and PPS in GC patients." (PMID 34650966, 2021). "We found 5 target gene candidates (Skp2, Psme3, Pik3cd, Klf4, and Hoxb5) that were consistently predicted by the three software and involved in tumor-related signaling pathway." (PMID 30967999, 2019). "In an experimental model, it was shown that a knockdown of the PSME3 gene reduced subcutaneous tumor growth rate and increased the number of CD8+ T-cells." (PMID 31877708, 2019). "Research on PSME3 within the domain of tumor immunity has been relatively limited in scope." (PMID 38312840, 2024). "Essentially, PSME3 serves as an oncogene, as is indicated by the existing studies, and promotes tumor apoptosis resistance, growth, and metastasis by modulating epithelial–mesenchymal transition, stem cell characteristics, and glycolysis in a Myc6-, Hippo-, or NF-kB13-associated manner." (PMID 34750284, 2022). "Furthermore, PSME3 plays a crucial role in regulating the cell cycle and inducing epithelial–mesenchymal transition to influence the tumor immune microenvironment in BRCA." (PMID 34650966, 2021). "Furthermore, clinical relevance indicated an association between high PSME3 expression and specific tumor staging (T1-T4/I/II/III/IV stages), irrespective of age." (PMID 38312840, 2024). "However, the prognostic value of PSME3 in pan-cancer and its involvement in tumor immunity remain unclear." (PMID 38312840, 2024). "The tumor-suppressive outcome is driven by combined molecular changes: downregulation of SPARCL1 and PSME3, coupled with upregulation of the NF-κB inhibitor NFKBIA and downregulation of CD44 and CCL15, collectively promotes apoptosis while suppressing proliferation, migration, and angiogenesis." (PMID 41465234, 2025). "CREB1 and CTSL1 were slightly overexpressed but not statistically significant, while PSME3 showed a significantly reduced level in RCC tumor tissues." (PMID 25784652, 2015).
cancer (27 papers, 2013 to 2025). A tumor composed of atypical neoplastic, often pleomorphic cells that invade other tissues. "PSME3 protein has been implicated in cancer by inhibiting c-Myc degradation and is a target gene of NF-κB during bacterial infections." (PMID 38132120, 2023). "YIPF6, TMEM9, and PSME3 have been associated with cancer and SPIRE1 reportedly contributes to metastatic potential." (PMID 30913233, 2019). "In summary, our study reveals the multifaceted role of PSME3 in cancer biology, immune regulation, and clinical outcomes, providing crucial insights for personalized cancer treatment strategies and the development of immunotherapy." (PMID 38312840, 2024). "Dong and colleagues made a report Comprehensive analysis of PSME3: from pan-cancer analysis to experimental validation." (PMID 39346927, 2024). "As immune infiltrating cells play a pivotal role in cancer development, we conducted an analysis to determine the estimated score, immune score, and stromal score of PSME3 in various cancers." (PMID 38312840, 2024). "Our research results indicate that abnormal PSME3 mRNA expression is observed in nearly all types of cancer within the TCGA dataset." (PMID 38312840, 2024). "We conducted a further analysis of the expression patterns of PSME3 in different cancers concerning pathological staging and metastasis." (PMID 38312840, 2024). "PSME3, the regulatory subunit of the proteasome, is an important oncogenic factor expressed in a variety of cancers, such as ovarian, breast and pancreatic cancers." (PMID 38561366, 2024). "When investigating the relationship between immune checkpoint expression and PSME3, we observed that among the 33 cancers, CD276 and CD274 exhibited the highest positive correlation with PSME3, followed by VEGFA, HMGB1, THR4, BTNA2, and ENTDD1." (PMID 38312840, 2024). "We conducted a pan-cancer analysis using the Kaplan-plot tool to assess the prognostic significance of PSME3." (PMID 38312840, 2024). "The analysis of the TCGA database reveals a significant upregulation of PSME3 gene mRNA expression in 15 distinct cancer types compared to normal tissues." (PMID 38312840, 2024). "In summary, our research revealed the multifaceted role of PSME3 in cancer biology, immune regulation, and clinical prognosis, providing crucial insights for the development of personalized cancer treatment strategies and immunotherapy research." (PMID 38312840, 2024). "PSME3 emerges as a key factor positively regulating the immune checkpoint CD276 in various cancers, including LIHC, LUAD, and BLCA." (PMID 38312840, 2024). "In this study, we conducted a comprehensive investigation aimed at exploring the differential expression of PSME3 in various cancers, its prognostic value, clinical pathological staging, metastasis, and biological functions." (PMID 38312840, 2024). "PSME3 holds the potential to become a significant target in future cancer therapies, but further research is needed to elucidate its detailed mechanisms and application prospects." (PMID 38312840, 2024). "Further research into the biological functions of PSME3 will contribute to the development of more effective cancer treatment strategies." (PMID 38312840, 2024). "In further analyses, we discovered a close correlation between high PSME3 expression and adverse clinical outcomes and cancer progression in LIHC." (PMID 38312840, 2024). "RNA interference-mediated silencing of PSME3 suppressed cancer cell proliferation, invasion and migration; induced cell apoptosis and cell cycle arrest at the G2/M phase; and enhanced radiosensitivity." (PMID 35270630, 2022). "Another chimeric transcript up regulated in our cancer samples is a fusion of the transcriptional regulator-encoding gene, RARA (retinoic acid receptor, alpha), with the 3′ UTR from the PSME3 (proteasome activator subunit 3) gene." (PMID 28851357, 2017).
cancer (continued). "This identified many genes, including CylinD1/D3, Cdk1/2, Psme3, Rad52/54L and Skp2 that have previously been shown to be dysregulated in cancer." (PMID 23762407, 2013). "It further indicated that PSME3 is a potential prognostic biomarker for various cancers." (PMID 38312840, 2024). "However, despite the previous reports on PSME3 in the mentioned cancer types, there hasn’t been a comprehensive pan-cancer study conducted to date." (PMID 38312840, 2024). "In our research, we have demonstrated that PSME3 could serve as a promising prognostic biomarker, especially in the context of future cancer immunotherapy, holding potential significance." (PMID 38312840, 2024). "Importantly, our immunohistochemical analysis provides further confirmation, strongly supporting the high consistency between PSME3 protein levels and mRNA expression across various cancer types." (PMID 38312840, 2024). "From the results, in 33 cancer types (excluding LGG), PSME3 was positively correlated with MMR gene expression." (PMID 38312840, 2024). "In comparison with the other PSM genes, differential expression of PSMB11 was relatively uncommon, whereas PSME3 and PSMG3 were found to be differentially expressed in virtually all examined cancer forms (15/16 cancer types)." (PMID 36123629, 2022). "Notably, higher levels of PSME3 exhibited a robust positive correlation with neutrophils, B cells, CD4 T cells, CD8 T cells, and M2 macrophages in cancers such as HNSC, KIRC, KICH, PRAD, and UVM." (PMID 38312840, 2024). "As PSME3 and PSMG3 are involved in proteasome activation and assembly, evaluation of their expression levels in cancer could be clinically relevant." (PMID 36123629, 2022). "This analysis showed that most PSM genes, especially PSME3 and PSMG3, were differentially expressed (frequently overexpressed) relative to normal tissue, further highlighting the importance of the proteasome in cancer development and progression." (PMID 36123629, 2022).
infection (5 papers, 2014 to 2025). The state of being infected such as from the introduction of a foreign agent such as serum, vaccine, antigenic substance or organism. "Three of these genes (Dcaf7, Dusp3, and Psme3) were down-regulated in susceptible vs. resistant mice at both pre- and post-infection time points by qPCR." (PMID 24901344, 2014). "Five genes in the QTL (Dcaf7, Dusp3, Fam134c, Psme3, and Slc4a1) were significantly differently expressed in a) susceptible vs. resistant mice, and b) humans with S. aureus blood stream infection vs. healthy human subjects." (PMID 24901344, 2014). "The proteasome has a recognized role in antigen presentation during infection but a role in direct bacterial killing has only very recently been described, coordinated by PSME3 and effected by proteasome cleaved antimicrobial peptides including PPP1CB, both prioritized in our analysis." (PMID 40447280, 2025). "We speculated that viral EBNA3B hijacks the ubiquitination of RNF41 by negatively interacting with PSME3, so that EBV induces other ubiquitin proteins to act at the first and second infection stages in the lytic phase." (PMID 30133498, 2018). "In addition, viral protein EBNA3B may hijack the ubiquitination function of RNF41 by negatively interacting with human protein PSME3, so that EBV exploits other ubiquitin proteins to carry out ubiquitination at both infection stages." (PMID 30133498, 2018).
bacterial infection (2 papers, 2022 to 2023). "The hematopoietic PSME3-deficient mice were more susceptible to bacterial infection, and increased bacterial burden in tissues." (PMID 35799836, 2022). "Studies have indicated that PSME3 is involved in the bacterial infection process." (PMID 35799836, 2022). "In addition, PSME3 also participates in the bacterial infection process." (PMID 35799836, 2022).
hematologic malignancy (1 paper, 2022). "Carfilzomib and Bortezomib, used to treat hematologic malignancy, have repurposing potential against PSME3 and PSMB5 dysregulation." (PMID 36293493, 2022).
PSME3 also shares sentences with these, for which no sentence is quoted: hepatocellular carcinoma (4 papers); melanoma (4); neurodegenerative disease (4); glioma (3); oral lichen planus (3); colon carcinoma (2); non-small cell lung carcinoma (2); oral cancer (2); acute myeloid leukemia (1); adult-onset Still disease (1); Anxiety (1); autoimmune disease (1); bladder cancer (1); Breast tumors (1); cognitive deficits (1); connective-tissue diseases (1); coronavirus disease 2019 (1); diffuse large B-cell lymphoma (1); endocarditis (1); gastric adenocarcinoma (1); head and neck cancer (1); head and neck squamous cell carcinoma (1); Hepatic steatosis (1); hepatitis B (1); hepatitis C (1); Infertility (1); Insulin resistance (1); invasive ductal carcinoma of the breast (1); kidney chromophobe (1); laryngeal carcinoma (1).
A further 25 diseases each share a sentence with PSME3 in 1 paper.